TMPRSS2 (transmembrane serine protease 2)
Diseases named in the same sentence as TMPRSS2 in open-access papers (continued):
Sharing a sentence is not in itself a finding about the gene and the disease.
prostate carcinoma (continued). "Of the 25 fusions not identified in RNA, 13 matched the characteristic tumor type of the known fusion pair (nine of which were TMPRSS2-ERG fusions in prostate cancer) and are likely to be pathogenic but with insufficient expression to be detected in the RNA." (PMID 36776527, 2022). "It was worth noting that TMPRSS2 is not only closely associated with the occurrence and progression of prostate cancer, but also can be used as an attractive therapeutic target." (PMID 34951103, 2022). "From our investigation it was found that 47 mutations occurred for TMPRSS2 in prostate cancer patients." (PMID 36239108, 2022). "They used this model to simulate numerous prostate cancer molecular changes, including but not limited to TMPRSS2-ERG fusion, SPOP mutation, SPINK1 overexpression, and CHD1 loss." (PMID 35813047, 2022). "This association can be explained by the high expression of TMPRSS2 in prostate cancer, and SARS-CoV-2 entry into the host cell." (PMID 34125851, 2021). "Since increased expression of TMPRSS2 stimulates androgen-driven prostate cancer progression, therapeutic approaches directed toward inhibition of TMPRSS2 have been suggested to reduce the risk of metastatic progression in patients with prostate cancer." (PMID 34399734, 2021). "A study conducted on a Japanese population indicated that the TMPRSS2 p.Val160Met variant (also known as Met160Val polymorphism) was associated with the risk of sporadic prostate cancer." (PMID 34001248, 2021). "Although several studies suggest that presence of these fusion genes in prostate cancer, TMPRSS2-ERG in particular, is associated with more aggressive malignancy and worse clinical prognoses, not all studies agree." (PMID 34573358, 2021). "So, the risk of lung cancer patients having TMPRSS2 expression is moderate but it is higher in prostate cancer patients." (PMID 33912588, 2021). "A TMPRSS2 SNP has been linked to TMPRSS2-ERG genetic fusion which is a frequent molecular event in prostate cancer." (PMID 33763088, 2021). "TMPRSS2 is also associated with prostate gland cancer cell expression, different complex(es) formation, human influenza and carcinoma, pathways in prostate cancer, influenza A, and transcriptional misregulation in cancer." (PMID 33609069, 2021). "The transcription of TMPRSS2 in the lungs is altered by the modulation of androgen and androgen derivatives causing a reduction in androgen levels in prostate cancer patients, which directly affects the chances of COVID-19 infection and severity in patients." (PMID 33912588, 2021). "Fusion events other than the TMPRSS2:ERG are also associated with the regulation of lncRNAs in prostate cancer." (PMID 33634124, 2021). "TMPRSS2 is a cellular enzyme encoded by the human TMPRSS2 gene involved in prostatic cancer and cleaving of hemagglutinin viral antigen and infectivity of HIN1 and H7N9 influenza virus." (PMID 34568081, 2021). "Changes in expression levels of TMPRSS2 have been previously associated with prostate cancer independently of SARS-CoV-2." (PMID 32974166, 2020). "It is expressed highly in prostate cancer and loss of TMPRSS2 in the prostate is associated with reduced metastatic potential." (PMID 32358833, 2020). "Other common prostate cancer associated genes such as TMPRSS2 and ERG show similar expression patterns." (PMID 33303959, 2020). "While PARP inhibitors have been tested in clinical trials and are a promising therapy for prostate cancer patients with TMPRSS2-ERG fusions and mutations in DNA repair genes, PARG inhibitors have not been evaluated." (PMID 32123273, 2020). "TMPRSS2 is a key gene in prostate cancer, which, as an associated translocation, drives ETS-family oncogene expression in a large proportion of tumors." (PMID 33092637, 2020).
prostate carcinoma (continued). "PRMT5 methylation of the TMPRSS2:ERG fusion protein is commonly seen in prostate cancer (PC) and implicated in prostate tumor formation by inhibiting AR -dependent transcription." (PMID 32743345, 2020). "The mutation profiles of six tumor-associated HGPIN lesions in a single case of TMPRSS2-ERG fusion-positive GS7 prostate cancer were evaluated." (PMID 31366128, 2019). "For example, TMPRSS2-ERG gene fusion is an early driver event in almost half of prostate cancer cases, and it often co-exists with copy number loss of PTEN and NKX3-1." (PMID 30978274, 2019). "At a frequency of almost half that reported for African Americans and roughly a quarter of that reported for men of European ancestry, acquisition of TMPRSS2‐ERG appears to be inversely associated with aggressive prostate cancer." (PMID 31090091, 2019). "Several studies have linked the presence of TMPRSS2-ERG with dismal outlook in prostate cancer patients, suggesting that the chimeric protein serves as a poor prognostic indicator." (PMID 31906059, 2019). "Urine exosome derived PCA3 and TMPRSS2-ERG have been found to associated with prostate cancer diagnosis and prostate cancer risk stratification." (PMID 31013716, 2019). "Correlative studies in human prostate cancers reveal a frequent association of the TMPRSS2/ERG (TE) fusion gene with loss of PTEN and studies in mouse models reveal that ERG expression and PTEN loss synergistically promote prostate cancer progression." (PMID 29581856, 2018). "Epidemiologic evidence shows that obesity is associated with a greater risk of aggressive prostate cancer (PCa) and PCa-specific mortality and this is observed mainly in men with the TMPRSS2-ERG gene fusion." (PMID 29163372, 2017). "And the most frequent prostate cancer fusion mutation, TMPRSS2-ERG, appears to have a remarkably higher iFCR value in all three independent patients." (PMID 29181411, 2017). "The most frequent fusion mutation in prostate cancer TMPRSS2-ERG shows higher iFCR value in all three independent patients." (PMID 29181411, 2017). "The comparison of FAM13C with established molecular features in prostate cancer demonstrated that increased FAM13C expression is strongly associated with the subset of tumors harboring the TMPRSS2:ERG gene fusion." (PMID 28415558, 2017). "The same study also showed that βIII-tubulin expression is strongly associated with ERG expression and TMPRSS2:ERG rearrangement in prostate cancer." (PMID 28677634, 2017). "Evidence of predisposition to TMPRSS2-ERG prostate cancer subtype was previously tested in small familial or sporadic small cohorts." (PMID 28663546, 2017). "In prostate cancers, TMPRSS2-ERG fusion caused by chromosomal translocation is present in approximately 50% of samples and manifests over-expression of a functional ERG transcription factor." (PMID 27191272, 2016). "For example, the TMPRSS2-ERG fusion transcript functions as a urinary biomarker for prostate cancer risk and prognosis and gene fusions are used in the diagnosis of a variety of cancers." (PMID 27105842, 2016). "The strong inverse association with TMPRSS2:ERG fusions identifies 6q15 deleted cancers as a significant subgroup among “non fusion-type” prostate cancers." (PMID 26684029, 2016). "The main objective of this study was to combine these techniques to investigate presence of the TMPRSS2-ERG gene fusion in two cohorts of human prostate cancer tissue and to identify its association to metabolism and biochemical recurrence." (PMID 27276682, 2016). "We also show a positive association with the highly prostate cancer-specific gene rearrangement between TMPRSS2 and the ETS transcription factor family member ERG." (PMID 26575822, 2015). "Such ethnical differences have been described for various relevant molecular cancer features, including HER2 amplification in breast cancer, TMPRSS2-ERG gene fusion in prostate cancer, and MET mutation in lung cancer." (PMID 26555375, 2015).
prostate carcinoma (continued). "CRISP3 has been reported to be one of the top genes that are linked to TMPRSS2-ERG positive prostate cancer with about 53-fold increase when compared with fusion negative prostate cancer." (PMID 24606912, 2014). "In both studies presence of the TMPRSS2-ERG fusion was associated with an increased risk of prostate cancer death." (PMID 24505269, 2014). "Intriguingly, SPOP mutations (function to stabilize AR) and TMPRSS2-ETS translocations are mutually exclusive in prostate cancer." (PMID 24508459, 2014). "The androgen-regulated TMPRSS2, however, is strongly associated with prostate cancer and forms a fusion gene with ETS transcription factor (TF) family members, that occurs in roughly half of prostate cancer cases." (PMID 25029565, 2014). "We have described current research of the cell-type-specific genome-wide binding patterns of ERG and regulating mechanisms by TMPRSS2-ERG encoded fusion products in prostate cancer cells." (PMID 24739220, 2014). "Other preclinical studies include radiosensitization by rucaparib, most evident in PTEN-deficient prostate cancer cells containing the TMPRSS2-ERG fusion gene." (PMID 24616882, 2014). "The present study suggests that the TMPRSS2-ERG fusion gene is associated with a more aggressive prostate cancer phenotype, supported by changes in the tumor stroma." (PMID 24505269, 2014). "In prostate cancer, genomic mutations of DNA repair-associated genes, such as polymerase iota, were positively correlated with TMPRSS2-ERG positive tumors, which associates ERG overexpression with the DNA damage response." (PMID 24504051, 2014). "In conclusion, we report here that overexpression of ERG transcription factor in TMPRSS2:ERG-positive prostate cancer induces a loss of DNA methylation at the TDRD1 promoter-associated CpG island." (PMID 23555854, 2013). "Plasma-Seq identified again multiple prostate cancer-associated chromosomal alterations, such as 8p loss, gain of 8q regions, the 3-Mbp TMPRSS2-ERG deletion on chromosome 21, and AR amplification." (PMID 23561577, 2013). "Further study into specific mechanisms of action of EZH2 have linked it with the gene fusion found in 50% of prostate cancers of TMPRSS2, an androgen-regulated gene, and the oncogenic ETS transcription factor ERG." (PMID 22641253, 2012). "According to long term clinical studies performed on a large cohort of patients, it seems that TMPRSS2/ERG expression is associated with a more aggressive form of prostate cancer." (PMID 21747944, 2011). "Previously it was reported that the majority of prostate cancers have a chromosomal rearrangement as a result of fusion of gene encoding TMPRSS2 with transcription factor ERG." (PMID 24213111, 2011). "Recent publications have reported that prostate cancer containing TMPRSS2-ERG fusions are significantly enriched for loss of the tumor suppressor PTEN." (PMID 21731703, 2011). "The inclusion of benign samples in our gene expression analysis additionally demonstrated that well-known biomarkers for prostate cancer like CRISP3 are associated with the TMPRSS2-ERG fusion status." (PMID 22142399, 2011). "TMPRSS2:ERG gene fusion mRNAs have been associated with aggressive prostate cancer morphology in tissues and a preliminary study using a combination of TMPRSS2:ERG plus PCA3 assays has shown synergistic diagnostic utility in urine specimens." (PMID 20598135, 2010). "TMPRSS2:ERG gene fusions have been associated with aggressive prostate cancer in a transgenic mouse model, detected in distant metastasis and also linked with aggressive prostate cancer phenotypes in humans." (PMID 20598135, 2010). "Recent studies have indicated that prostate cancer patients with the TMPRSS2–ERG gene fusion have a higher risk of recurrence." (PMID 20068566, 2010). "Around 60% of prostate cancers are reported to contain fusions of the androgen regulated gene TMPRSS2 to ERG9, 11–14 which causes high level expression of 3′-ERG gene sequences." (PMID 19638540, 2009).
prostate carcinoma (continued). "The first target sequence for miRNA assay development was derived from searches in the regions of TMPRSS2 and Ets family member chromosomal breakpoints (21q21.2–21.3) because this region has been associated with aggressive forms of prostate cancer." (PMID 19267923, 2009). "To examine further these associations, we sought the presence of TMPRSS2:ERG gene fusion in 165 frozen prostate cancer samples from patients who underwent radical prostatectomy for localised prostate cancer." (PMID 17971772, 2007). "We conducted a survival analysis to determine the prognostic significance of the presence of the TMPRSS2:ERG fusion gene on the risk of prostate cancer recurrence, adjusting for the established prognostic factors." (PMID 17971772, 2007). "Androgen deprivation therapy (ADT), widely used in prostate cancer treatment, may potentially modulate TMPRSS2 expression, affecting SARS-CoV-2 infection susceptibility and severity." (PMID 41150771, 2025). "TMPRSS2 has been identified in EVs associated with prostate cancer." (PMID 40214422, 2025). "The increasing incidence of prostate cancer in Pakistan, with one study showing a rise from 3.88% to 5.80% between 2000 and 2023, is attributed to factors such as aging, obesity, smoking, and genetic predispositions such as the TMPRSS2 gene polymorphism." (PMID 39670291, 2025). "Due to its high frequency in prostate cancer cases, the TMPRSS2:ERG fusion might be more promising as a diagnostic marker rather than as prognostic." (PMID 37511059, 2023). "The unfavorable clinical outcome observed in these patients seems to be strongly influenced by the androgen receptor signaling, a hallmark of prostate cancer, as androgens enhance the expression of the type II protease, TMPRSS2, and suppress the innate and adaptive immune responses." (PMID 36836943, 2023). "In addition, more than 50% of cases of prostate cancer are associated with the TMPRSS2-ERG fusion gene rearrangement." (PMID 37735473, 2023). "CAG repeats may be associated with TMPRSS2: ERG fusion-positive prostate cancer, but may be protective against PC in China." (PMID 36824501, 2023). "The findings of this study suggest that a distinct group of young patients with aggressive prostate cancer is frequently associated with TMPRSS2:ERG fusions, while exhibiting a lower likelihood of harboring mutations in other genes, such as AR, SPOP, and ASXL1." (PMID 37511059, 2023). "Conversely, in a different study, TMPRSS2:ERG fusion detected by RNA sequencing in prostate cancer samples was associated with a lower lymphocytic infiltration, a finding that could potentially interfere with the biology of the tumor immune response." (PMID 37511059, 2023). "TMPRSS2 is implicated in depression associated with prostate cancer." (PMID 35444632, 2022). "To understand the possible causes of prostate cancer patients' increased vulnerability and mortality from COVID-19 infection, we focused on the two most important agents, transmembrane protease serine subtype 2 (TMPRSS2) and the C-X-C motif 10 (CXCL10)." (PMID 36239108, 2022). "Forty-seven mutations were found in 30 locations of TMPRSS2 protein in prostate cancer patients." (PMID 36239108, 2022). "However, prostate cancer is associated with overexpression and a more diffuse localization pattern of TMPRSS2." (PMID 35163273, 2022). "Both AR and TMPRSS2 are implicated in prostate cancer, and some data suggests that there may be an association between prostate cancer and depression and anxiety." (PMID 35444632, 2022). "Considering TMPRSS2 is mainly expressed in prostate cancer, we conclude that CTSL mutations primarily correlated with FURIN expression, which might further regulate SARS-CoV-2 entry in cancers." (PMID 35414771, 2022).
prostate carcinoma (continued). "Further, high expression of ACE2 in the male urogenital system organs, including the prostate, and the overexpression of androgen receptor-regulated TMPRSS2 in prostate cancer patients, could increase their susceptibility to SARS-CoV-2 87-89." (PMID 33391502, 2021). "This variant affects a residue far from the serine protease catalytic triad and was previously found to be significantly associated with TMPRSS2 rearrangements linked to the risk of prostate cancer and a relatively shorter time to diagnosis for high-risk patients." (PMID 34356057, 2021). "Moreover, the TMPRSS2-ERG fusion event is associated with overexpression of the oncogene MYC in prostate cancer cells, which further contributes to promote cell growth and proliferation." (PMID 34638309, 2021). "The p.Val160Met variant has recently been found to be associated with a mutation in TMPRSS2, particularly in terms of the risk of prostate cancer and the examination of this variant in patients may shorten the diagnosis time in high-risk individuals." (PMID 34803443, 2021). "Moreover, due to higher insulin/insulin-like growth factor signaling, men with prostate cancer harboring the TMPRSS2-ERG gene fusion are more susceptible to obesity and hence have poorer prognosis than those not harboring the gene fusion." (PMID 34001144, 2021). "We then hypothesize that coronavirus infection, related at least in part to TMPRSS2 expression, might be associated with prostate cancer risk to some extent." (PMID 32970391, 2020). "Studies have linked TMPRSS2 to prostate cancer via a chromosomal translocation resulting in the fusion of the TMPRSS2 promoter-enhancer with the Erythroblast Transformation Specific (ETS) transcription factors ETS-related gene (ERG) and ETS translocation variant 1 (ETV1)." (PMID 32974166, 2020). "Here, we highlight the relevant association of TMPRSS2 with prostate cancer." (PMID 32970391, 2020). "MTAP-ANRIL fusion has been reported in melanoma and CLDN18-ARHGAP26 in gastric cancer, the latter promoting loss of the epithelial phenotype in gastric cancer.TMPRSS2 fusions may be defining markers for prostate cancer." (PMID 31007851, 2019). "PCA3 and TMPRSS2-ERG in combination with the Prostate Cancer Prevention Trial risk calculator may help in deciding the urgency of biopsy after an elevated serum PSA." (PMID 31013716, 2019). "Increased ROCK1 expression was associated with TMPRSS2:ERG fusion positive prostate cancers." (PMID 31557128, 2019). "Previous studies showed that prostate cancers could be grouped by various somatic mutations including TMPRSS2:ERG fusions and PTEN, 3p13, 5q21 and 6q15 genomic deletions." (PMID 30823906, 2019). "In prostate cancer, new loops with specific histone modifications may serve as new diagnostic markers; the TMPRSS2-ERG fusion has been used as a marker in diagnosis and risk assessment for many years, even before chromatin loops were identified as the culprit." (PMID 29149895, 2017). "The difference of TMPRSS2-ERG fusion transcripts between KANSARL-positive and KANSARL-negative tumors is significant (Fisher's exact test, p<0.001), indicating that KANSARL fusion transcripts are associated with prostate cancer biomarker TMPRSS2-ERG fusion transcripts in the VPD tumor patients." (PMID 28881586, 2017). "Furthermore, in prostate cancer, βIII-tubulin expression is associated with both TMPRSS2:ERG rearrangement, ERG expression and PTEN deletions, three key oncogenetic features in metastatic prostate cancer." (PMID 28677634, 2017). "TMPRSS2:ERG gene aberration may be a novel marker that improves risk stratification of prostate cancer before definitive cancer therapy, but studies have been inconclusive." (PMID 27377958, 2016). "Therefore, to introduce a personalised treatment for patients with prostate cancer, we focused our targeted therapy by silencing TMPRSS2-ERG variants III and IV." (PMID 25933120, 2015).